IL6 (interleukin 6)
Diseases named in the same sentence as IL6 in open-access papers (continued):
Sharing a sentence is not in itself a finding about the gene and the disease.
tumor (continued). "Other studies demonstrated that resistant exercise on the animal cancer model mitigates tumor growth, tumor grade, viable tumor area, tumor cell proliferation, and myofiber atrophy-causing cancer cachexia via attenuating some key markers such as TNF-α, IL-6, Atrogin1, and oxidative damage." (PMID 35801156, 2022). "IL-6 enacts a broad set of physiological functions traditionally related with immune cell regulation, host defense, proliferation and differentiation, and can directly stimulate the proliferation, survival, metastasis and invasion of tumor cells." (PMID 36591515, 2022). "The activation of the complement system has become a mediator in anti-tumor treatment, which also increases the secondary inflammatory mediators, such as cytokines IL-1β, IL-6, IL-10, TNF-α, and G-CSF, leukotrienes, thromboxane, prostaglandins, histamine, and coagulation factors." (PMID 35692783, 2022). "CSCs can not only transform into cancer cells and enhance their resistance to chemoradiotherapy, but also secrete immunosuppressive cytokines such as transforming growth factor-β (TGF-β), interleukin-6 (IL-6), IL-10, and IL-13, which can induce immune evasion of tumor cells." (PMID 36176299, 2022). "Interestingly, IL6/STAT3 signaling has been shown to play a role in tumor progression by inducing epithelial to mesenchymal transition and angiogenesis." (PMID 35327992, 2022). "IHC results illustrated that anti-IL-6 antibodies could significantly downregulate PD-L1 expression in tumor cells and decrease the infiltration of M2 macrophages, MDSCs, and Treg cells." (PMID 35550592, 2022). "Since multiple secreted factors identified above, including AREG, PAI-1, CCL2, CCL5, IL6, IL8, and CSF2, are also known to be regulated by yes associated protein (YAP), we investigated whether V2R regulates YAP in ccRCC tumor cells." (PMID 35886951, 2022). "IL-6 also could induce tumor cell growth, metastasis, and angiogenesis through IL-6R-mediated pathways." (PMID 35513871, 2022). "In addition, IL6 produced by inflammatory and tumor cells is able to induce POSTN production by CAFs via STAT3 signaling." (PMID 35567669, 2022). "Taken together, all these findings indicate that interleukin-6 might be an important factor for tumor cell growth, angiogenesis, metastasis and spheroid formation." (PMID 35252204, 2022). "Furthermore, the promoting effect of MSCs on tumor can be eliminated by knockout the expression of IL-6 in MSCs." (PMID 36439438, 2022). "However, adjacent tumor regions with reciprocal expression of pSTAT3 and IL-6 was also observed in a HER2neg tumor (Pattern 3)." (PMID 35565421, 2022). "Interestingly, we found that the tumour expression of fucosylation-related genes is negatively correlated with pro-inflammatory cytokines IL-8 and IL-6 in macrophages, while showing a positive correlation with TGF-β." (PMID 35017635, 2022). "However, some tumor-infiltrating DCs become suppressive in the presence of cytokines such as IL-6 and M-CSF secreted by cancer cells and inhibit anticancer immunity by inactivating immune cells." (PMID 36345336, 2022). "UCMSCs-Tandab(IL-6/CD20), which bound with both tumor-associated surface antigens and pro-tumor cytokines in tumor microenvironment, might serve as a potential treatment for DLBCL, evidenced by inhibiting the growth of SU-DHL-2 or SU-DHL-4 cells." (PMID 36104733, 2022). "The NF-κB/IL-6/STAT3 signaling cascade was closely associated with the inflammatory response, which induced proliferation and remodeling of epithelial cells and then promoted tumor development." (PMID 35991881, 2022). "Then, the PLVAP+ ECs may express IL6 to activate TAMs, which, in turn, maintain an immunosuppressive tumor microenvironment via the IL10–IL10RB axis." (PMID 36238304, 2022).
tumor (continued). "However, a key cytokine, whose function further demonstrates the crucial roles of inflammation in sustaining tumor growth, is IL-10, which inhibits the inflammatory effects of IL-6 and IL-12/IL-23 and inhibits tumor-promoting inflammation." (PMID 35158821, 2022). "However, inflammatory mediators known to be involved in tumor progression and angiogenesis, such as IL-6 and VEGF were elevated in patients with EHMS, which was also observable for IFN-γ." (PMID 36230528, 2022). "Besides, in tumor cells, chronic stress mediated by β2-AR promoted the release of IL-6 and activated the JAK-STAT3 signaling pathway." (PMID 35517411, 2022). "Therefore, we concluded that IL-6 upregulated expression of PD-L1 in tumor via the JAK1/Stat3 signaling pathway." (PMID 35550592, 2022). "However, more recent studies show IL-6 signaling can inhibit tumor growth by enhancing the tumor and lymph node trafficking of cytotoxic T cells." (PMID 36551577, 2022). "Tumours may reprogramme MSCs to recruit them to the tumour site, where they play a tumour‐supportive role via secretion of exosomes, IL‐6, SDF‐1, PDGF and HGF in several cancers." (PMID 35908277, 2022). "CXCL13 may then act as a protumour factor and, with IL-6, promote B cell responses which also act on tumour growth." (PMID 35226704, 2022). "IL-6 is closely related to changes in the tumor microenvironment." (PMID 35267605, 2022). "In addition to being relevant in the course of tumorigenesis, IL-6 also facilitates the series of events that must occur as a prerequisite for the formation of a secondary tumour, a metastasis." (PMID 36429126, 2022). "Leptin did not associate with changes in tumor burden; however, circulating IL-6 was elevated in VSG mice." (PMID 35775614, 2022). "Local IL-6-driven inflammation may have direct growth effects on the cancer cells and indirect tumor-promoting effects on the bone marrow microenvironment (e.g., through tolerogenic polarization of antigen-presenting cells)." (PMID 36371231, 2022). "Finally, knockdown of Sox4 suppressed OSCC growth in vivo, and antagonized the acceleration of IL-6 on tumor growth." (PMID 35513871, 2022). "Indeed, cooperativity between orally-delivered 1MT and subcutaneous administration of gDE7 in IL-6-/- mice induced tumor rejection and DC activation." (PMID 36405719, 2022). "Therefore, what is of particular interest in the area of cancer research are the effects of IL-6 on both stromal and parenchymal cells in promoting the invasiveness of the tumour and its ensuing metastasis." (PMID 36429126, 2022). "Indeed, previous studies found that the pro-tumorigenic role of IL-1β was also related to its ability to induce tumour cells to produce other cytokines, including IL-6." (PMID 35326545, 2022). "The predominant role of IL-6 in cancer is its key promotion of tumour growth." (PMID 35924148, 2022). "Current studies have found that IL-17 could promote tumor growth through IL-6-Stat3 signaling pathway, and also release IFN-γ and other cytokines through stimulating T cells, dendritic cells, NK cells and other immune cells, thus inhibiting tumor growth." (PMID 36246294, 2022). "Several studies have reported on the tumor‐derived IL‐6 in various cancer cells." (PMID 35578571, 2022). "Likewise, oral administration of β-1,3-Glucan derived from yeast (Saccharomyces cerevisae) in tumor-bearing mice stimulates granulocyte-macrophage progenitors and active cytokines such as IFN-γ, IL-1α, and IL-6, suppressing tumor progression." (PMID 35401838, 2022). "In this study, we found that FAVO significantly promoted the expression of tumor IL-2 and IFN-γ, and inhibited the level of IL-6, which may be the mechanisms underlying the antitumor effects of FAVO." (PMID 35392643, 2022). "Since IL-6, which is a widely studied NF-κB effector, is closely related to tumour progression, we sought to determine whether its expression level was associated with PCDH1 in PDAC tissues." (PMID 35864095, 2022).
tumor (continued). "At first, the expression of inflammatory factors IL-6, TNF-α and IL-10 is increased, suggesting that HCC cells may induce Mφs to trend towards tumor-associated macrophages (TAMs), thus promoting disease progression." (PMID 36032078, 2022). "Previous studies have focused on STAT-3, IL-6R and IL-6 pathways as enhancers of tumor progression." (PMID 35703345, 2022). "Blockade of IL-6 and PD-1 produced anti-tumor activity in several mouse models." (PMID 36077755, 2022). "Furthermore, a higher abdominal metastasis rate was presented in the circCUL2 group than in the control group, while treatment with the anti-IL6 antibody significantly inhibited tumor growth and abdominal metastasis." (PMID 35189958, 2022). "The association of M1-like macrophages with tumor metastasis may be partly due to the effects of inflammatory cytokines, such as IL-1β, TNF-α, and IL-6, which directly or indirectly contribute to vasoproliferation." (PMID 35844605, 2022). "Furthermore, an in vivo study demonstrated that combined administration of NVP-BEZ235 and anti-IL-6 Ab reduced HCC tumour load more effectively than either NVP-BEZ235 or anti-IL-6 Ab treatment alone." (PMID 35165269, 2022). "IL-6 is a critical pro-inflammatory factor mainly derived from tumor cells, CAFs, and TAMs." (PMID 35953863, 2022). "Moreover, elevated IL-6 and decreased IL-15 in pre-cachetic and cachetic patients can alter the function of immune cells, which resulted reduced anti-tumor effect." (PMID 35538112, 2022). "Indeed, there is growing evidence that acidification decreases the expression of CCL2, IL-6, and iNOS in M1 macrophages while increasing the expression of markers in M2 macrophages within the tumor milieu." (PMID 35646923, 2022). "Hence, targeting specific components of SASP, such as IL-6 or IL-8, serves as another strategy to reverse the tumor-propagating or enhance the tumor-suppressing function of SASP." (PMID 36611926, 2022). "However, Th2 cells release the cytokines IL-4, IL-6, IL-10, and IL-13, which stimulate M2 TAMs, inducing tumor promotion and downregulating antitumor immunity." (PMID 36380016, 2022). "Furthermore, non-small-cell lung cancer-derived exosomes are found to be rich in miR-21 and miR-29a, which recruit macrophages and bind to TLR-8 to promote the secretion of IL-6 by immune cells, promoting the proliferation and migration of tumor cells." (PMID 35741075, 2022). "However, corylin inhibited the mRNA expression and protein levels of Ifnγ, Tnf-α, Il-6, Il-1β, Nlrp3, Asc, Pannexin, and Pro-caspase 1 in the tumor tissues of AOM/DSS-induced CAC mice." (PMID 35269806, 2022). "Activation of this IL-6/STAT3 axis-guided fructose metabolism promotes tumor cell growth." (PMID 35813468, 2022). "In addition, the mRNA of inflammatory cytokines IL-1 β and IL6, as well as macrophage cell surface marker F4-80, were found to be elevated in tumor-bearing PE-infused mice." (PMID 35406672, 2022). "Thus, our data suggests that activated macrophages derived IL-6 have the ability to induce tumor growth by inducing cell proliferation which is evident by enhanced Ki67 expression in activated macrophage derived CM treated tumors." (PMID 35300689, 2022). "IL-6 effects in this context included local changes in tumor cell-cell and cell-substrate adhesion, enhanced motility, epithelial to mesenchymal transformation (EMT), and changes in cell proliferation rates in both solid tumors as well as hematologic dyscrasias." (PMID 35406728, 2022). "The method has been validated for detecting an inflammatory factor, human interleukin-6 (human IL-6), and a tumor marker, human vascular endothelial growth factor (human VEGF), with LODs of 45.81 and 32.27 fg/ml, respectively, thereby achieving a hundredfold improvement in LOD." (PMID 36185462, 2022).
tumor (continued). "IL-6 plays an important role in T-cell proliferation, survival, and trafficking to the tumour site." (PMID 35740353, 2022). "We next sought to determine whether IL6 secreted by FAK-wt cells was also required for PD-L2 expression in Panc47 tumours." (PMID 36138073, 2022). "CASP8, CASP6, GSDME, NOD1, and GPX4 were significantly upregulated in tumor tissues compared to the normal tissues, whereas IL6, IL1B, NLRP3, and NLRC4 were downregulated, suggesting that pyroptosis-related genes play important roles in tumor progression and prognosis." (PMID 35559014, 2022). "A dual function of IL-6 and M-CSF in tumor promotion is that they inhibit CD34+ progenitor differentiation into DCs but then induce their commitment towards CD14+ monocytes with an effective phagocytic capability but lacking APC functionality, thus failing to mediate allogeneic T-cell proliferation." (PMID 35784290, 2022). "IL6 can also regulate tumor treatment resistance, such as multidrug resistance." (PMID 35962042, 2022). "STOML2 promotes tumor progression by upregulating IL-6 to promote STAT3 pathway." (PMID 35851063, 2022). "However in this review, IL-6 trans-signalling through a soluble form of the IL-6Rα is involved in inflammation driven tumor response." (PMID 35844493, 2022). "Importantly, IL-6 level decreased in the plasma of N6L-treated mice compared to control tumour-bearing mice." (PMID 36077801, 2022). "Moreover, in general, there is not only a unilateral influence of IL-6 on the composition and activation of the CRC immune microenvironment, but IL-6-mediated signaling is conversely also controlled by components of the tumor micromilieu." (PMID 36428508, 2022). "In addition, TNF-3 enhances tumor angiogenesis through various angiogenic factors, including IL-6, IL-8, and VEGF." (PMID 36578029, 2022). "Furthermore, IL-6 and IL-10 cytokines are involved in macrophage polarization towards M2 phenotype and hence promote tumor growth." (PMID 33783686, 2021). "Indeed, the secretion of pro-inflammatory cytokines IL-6, IL-11, TNFα, and IL-1β enhances tumor cell proliferation through the signal transducer and activator of transcription 3 (STAT3) and the anti-apoptotic nuclear factor κB (NF-κB)." (PMID 34680425, 2021). "Although type Th2-type cytokines such as IL-4, IL-5, IL-6, IL-10, and IL-13 are more involved in host anti-parasitic defense and allergic reactions, evidence suggests that they can elicit anti-tumor responses via eosinophils activation as well as stimulating antibody production." (PMID 34868907, 2021). "In addition, IL6 upregulates Mcl-1 (an apoptosis inhibitor) enhancing tumour cells survival by increasing expression of STAT3." (PMID 33579265, 2021). "In particular, it has been demonstrated that the activation of the transcription factor Nuclear Factor-κB (NF-κB) in the tumor site results in production of pro-inflammatory cytokines like IL-6 and IL-1, which support proliferation and survival of cancer cells." (PMID 34113338, 2021). "Indeed, it has been found recently that elevated IL6 levels in blood plasma resulted a STAT3 hyperactivation in tumor cells." (PMID 33578642, 2021). "Furthermore, as an integral part of the TME and a large producer of the ECM, cancer associated fibroblasts (CAFs) release IL6, chemokine (C-C motif) ligand 2, and C–X–C motif chemokine ligand 12 (CXCL12) that eventually support tumor growth and metastases." (PMID 34205944, 2021). "Additionally, immunohistochemistry (IHC) analysis in resected specimens of biliary cancer showed TGF-β and IL-6 staining not only in the invasive margins of the tumour but also in the invading cancer cells in the bile duct." (PMID 34361105, 2021). "Other factors in the tumor microenvironment that will lead to drug resistance include the presence of overexpressed growth factors such as vascular endothelial growth factor and cytokines including interleukin-6 (IL6) and nuclear factor-κB (NF-κB)." (PMID 33499040, 2021).
tumor (continued). "The appearance of a peripheral blood smear that has been influenced by IL-6 activation within the tumor microenvironment may predict the degree of inflammation, which in turn affects tumor progression and survival." (PMID 34751228, 2021). "Besides, in addition to immune cells, cytokines such as interleukins (IL)-4 and IL-6 also play a prominent role in the process of tumor immunity." (PMID 34568032, 2021). "It has been suggested that IL-6 could be a biomarker of a more aggressive tumour biology and that higher IL-6 concentrations are also correlated with impaired survival in several other cancer types as well." (PMID 34359796, 2021). "The number of M2 macrophages is relatively low at the early stages of CRC, so IL-6 could be produced by tumor cells and M2 macrophages, creating propel wheel for further tumor growth." (PMID 35008550, 2021). "The increased IL-6 from MSC promotes tumor growth, STAT3 activation, and lung metastasis from OS." (PMID 34681692, 2021). "Different mechanisms are involved in IL-6’s antitumor activity, such as the promotion of macrophage and lymphokine-activated killer cell antitumor activities, as well as an increase in neutrophils’ cytotoxic effects on tumor cells." (PMID 33923292, 2021). "Combination of IL-6 inhibition with CD40 stimulation reverses Mφ-mediated tumor immunosuppression, sensitizes tumors to checkpoint blockade, and extends animal survival in two syngeneic GBM models, particularly inducing complete regression of GL261 tumors after checkpoint blockade." (PMID 34103524, 2021). "This study suggested that cryosurgery generates the most favourable immune-regulatory response for abscopal tumours and activation of anti-tumour immune cells, and increased secretion of pro-inflammatory cytokines such as IL-1β, IL-2, IL-6, IL-12β, IFN-γ and TNF-α." (PMID 34281259, 2021). "On the other hand, the phenomenon in patient #3 suggested that IL6/IL1 blockers were secreted from CART cells in a transient manner only when CART cells were actively killing tumor targets, significantly relieving the concern of compromising patient immunity after CART treatment completed." (PMID 33907185, 2021). "Strong IL-6 expression was observed in fat from KPC tumor–bearing mice." (PMID 33851955, 2021). "Rapid production of IL-6 contributes to host defense during infection and tissue injury, but excessive synthesis of IL-6 and dysregulation of IL-6R signalling is often involved in disease pathology such as tumour progression and metastasis." (PMID 34223877, 2021). "Anti-IL-6 antibodies are able to mitigate tumor cachexia in a mouse model of colon cancer." (PMID 34899373, 2021). "Different sources of IL6 can induce a tumour-promoting effect in BC cells." (PMID 34834425, 2021). "Additionally, in the tumor microenvironment, the secretion of proinflammatory cytokine IL-6 increased, while the secretion of immunosuppressive cytokine IL-10 was downregulated." (PMID 34575449, 2021). "Furthermore, increased secretion of MCP-1, MIP-2, and IL-6 also mediated a chemotactic role in increasing the infiltration of macrophages and inflammatory cells into the tumor." (PMID 34440886, 2021). "However, PDAC cells and the TME rather promote differentiation of TH2 cells which are regarded as immune-suppressing and thereby tumor-promoting, mainly because of the release of cytokines like IL-4, IL-5, IL-6, IL-10 and IL-13." (PMID 34638420, 2021). "IL-6 could also mediate the interaction between cancer cells and CAFs not only by supporting tumour cell growth but also by promoting fibroblast activation in oesophageal cancer." (PMID 33824303, 2021). "An upregulation of IL-6 has been reported in several kinds of malignancies, and works as a tumor promotor in the tumor microenvironment through multiple pathways including the NF-kB and MAPK/ERK signaling pathway, including promotion of proliferation, angiogenesis and invasiveness." (PMID 34574641, 2021).